RAD21 (RAD21 cohesin complex component)
Diseases named in the same sentence as RAD21 in open-access papers (continued):
Sharing a sentence is not in itself a finding about the gene and the disease.
cancer (continued). "Interestingly, altered RAD21 or SMC1A expression was also reported as associated with distinct cancer phenotypes, although the complete mechanism of cohesin biology remains to be determined." (PMID 25963978, 2015). "A comparison of gene expression profiles of FACS-sorted double positive keratinocytes isolated from UV-treated WT and TG mice indicated increased expression of Pes1, Rad21, Tfdp1, and Cks1b genes in TG mice linked to cell transformation, invasion, and metastasis of cancer cells." (PMID 23738074, 2013). "We previously found Rad21 variants in cancer patients exhibiting acute radiation toxicity, suggesting an association between Rad21 gene variants and normal tissue protection that may be defective in some radiation sensitive cancer patients." (PMID 20711430, 2010). "However, whether DNA variants outside of the RAD21 gene could control its expression and thereby contribute to cancer and developmental disease is unknown." (PMID 35906355, 2022). "Furthermore, as prior researchers have hypothesized, SQLE expression together with overexpression of other nearby genes including RAD21, which encodes a protein involved in DNA repair, could work to promote a more aggressive cancer phenotype." (PMID 29228969, 2017). "Collectively, ours and other data highlight the likely effects of the DNA repair functions of RAD21 in tumor biology, and their potential importance in cancer treatment, although other aberrant functions of RAD21 could theoretically contribute to our observed associations and phenotypes." (PMID 21255398, 2011). "The down-regulation of RAD21 expression has been observed to result in the loosening of chromatin interaction, the promotion of mesenchymal phenotypes, and the acquisition of cancer stem cell properties." (PMID 40642059, 2025). "Across all assessed genes, the mutation landscapes of stage I-III and stage IV cancers were highly similar with the exception of more frequent alterations in RAD21 in stage IV HR+/HER2− cancers." (PMID 40421962, 2025). "A number of these newly liganded cysteines are on proteins associated with gene expression and regulations, as well as cancer drivers including POLRMT and RAD21 which are potential hotspots for therapy." (PMID 37322008, 2023). "The study of 94 familial breast cancers demonstrated RAD21 overexpression in 43%, 44% and 33% of BRCA1, BRCA2 and BRCAX tumours, respectively, and expression was associated with shortened cancer-specific overall survival (Hazards Ratio 1.66, p = 0.003)." (PMID 36831687, 2023). "Up-regulated RAD21 in HeLa cells leads to compartment switching and up-regulation of cancer-related genes." (PMID 37381036, 2023). "Intriguingly, in human cancer cells, the cohesin component Rad21 and the chromatin organizing factor CTCF bind to TERRA promoters and control TERRA transcription." (PMID 37636218, 2023). "Beyond the three LoF-intolerant genes, three other RAD21 co-regulated genes also have putative roles in cancer." (PMID 35906355, 2022). "In this study, we searched for genomic variants that modify RAD21expression to determine their potential to contribute to development or cancer by RAD21 dysregulation." (PMID 35906355, 2022). "OS PDXs also had increased MYC and RAD21 copy number gains (3–7 copies), both of which are known cancer markers with multi-functions leading to increased DNA replication and oncogenic-induced replication stress, a hallmark of aggressive OS." (PMID 36612255, 2022). "The CNV analysis by sequencing (CNV-seq) revealed five cancer-associated genes as the most frequent with gains (NOTCH1, MYC, NUMA1, PLAG1, and RAD21), while 30% of the tumors showed SMARCA4 with loss." (PMID 35884575, 2022). "Blocking the Akt/mTOR signaling pathway reversed RAD21 overexpression-induced cancer progression and drug resistance." (PMID 35860572, 2022). "In cancer, alteration of RAD21 expression is closely related to the development, prognosis, invasion, and metastasis of cancer cells." (PMID 35906355, 2022).
cancer (continued). "Among them, five cancer-associated genes were confirmed by both analyses as the most frequent genes with gains: NOTCH1, MYC, NUMA1, PLAG1, and RAD21." (PMID 35884575, 2022). "Pan-cancer analysis of TCGA data revealed that RAD21 amplification occurs most frequently in OV (21%) compared with 31 other cancer types." (PMID 36201246, 2022). "This suppression of the RAD21 gene also enhanced the cytotoxicity of etoposide and bleomycin (two DNA-damaging chemotherapeutic agents), which revealed that by the induction of DNA damage, RAD21 can be a novel target for developing cancer therapeutics." (PMID 35205681, 2022). "The WES also allowed us to identify CNV-seq in 42 cancer-associated genes with cn > 3, including NOTCH1, MYC, NUMA1, PLAG1, and RAD21 amplified in 10% of tumors." (PMID 35884575, 2022). "RAD21 is often overexpressed in highly replicative cancers and it has been reported that RAD21 is amplified in OS and other cancers." (PMID 32859084, 2020). "According to this model increases in inflammation signaling would be a relevant mechanism driving selection of Rad21/cohesin mutant cells at early stages of cancer development." (PMID 30530755, 2019). "Rad21 is known to be highly expressed in some malignant tumors and is related to the biological behaviors of tumors." (PMID 29797792, 2018). "This further supports our argument that BRCA1 cancers behave differently from other cancers in response to RAD21 overexpression." (PMID 22537934, 2012). "A meta-analysis of gene-expression data from clinical cancer specimens showed that increased RAD21 expression was a feature of poorly differentiated breast, ovarian, bladder, and lung cancers." (PMID 22537934, 2012). "In these cancers, we also correlated RAD21 expression with genomic expression profiling and gene copy-number changes and miRNAs predicted to target RAD21." (PMID 22537934, 2012). "In a mega-scale microarray analysis of multiple cancers, RAD21 was identified as one of 69 signature genes in undifferentiated cancers that had aggressive in vitro or clinical courses and poor patient outcomes." (PMID 21255398, 2011). "Clinical RS and its unfortunate functional consequences for cancer patients also provide a rationale for a predictive assay for testing for Rad21 status prior to RT, as a form of molecularly individualized medicine." (PMID 20711430, 2010). "Indeed, we found that several cancer-related genes were recurrently hit by somatic variants in multiple non-cancer blood samples, including three previously reported CHIP genes: IGLL5, RAD21, and IDH2." (PMID 41505106, 2026). "The significant activation of RAD21-extended(57g) in Malignant_CS4 may reflect increased chromosomal instability, a common feature of many cancers." (PMID 40170854, 2025). "How cancer cells circumvent the transcriptional and degradational mechanisms that normally regulate RAD21 levels remains unclear, but reducing RAD21 levels in cancer cells appears effective in reducing cell proliferation and/or inducing apoptosis." (PMID 41370327, 2025). "The identification of surveillance mechanisms that target Mcd1/RAD21 may significantly impact studies of both human development and cancer progression." (PMID 41370327, 2025). "This suggests a mechanism of chemotherapy resistance in BRCA2 and BRCAX cancers, which may be abrogated in BRCA1mut tumours, most likely due to inherent inactivation of RAD21, as BRCA1wt has been shown to be required to activate RAD21 function." (PMID 36831687, 2023). "A combination of inhibiting the RAD21-mediated DNA damage repair pathway with PARP inhibitors may be a new therapeutic strategy for HR-proficient cancers." (PMID 35860572, 2022). "However, their regulatory relationships with RAD21 open up novel avenues for exploration of disease onset for both cohesinopathy disorders and cancer." (PMID 35906355, 2022).
cancer (continued). "Furthermore, we verified a role of RAD21 in suppressing cancer immune response, which engenders an immunosuppressive tumor microenvironment with poor infiltration of cytotoxic T cells." (PMID 36201246, 2022). "Functionally, RAD21 overexpression promoted cancer cell proliferation, migration, and invasion." (PMID 35860572, 2022). "Therefore, amongst all cohorts, RAD21 p.P298S/A was found to be enriched in pediatric vs. adult cancers (3/482 vs. 1/2300; Fisher’s exact test; p = 0.018)." (PMID 35563565, 2022). "Notably, RAD21 depletion significantly increased PD-L1 expression in both human and murine cancer cells." (PMID 36201246, 2022). "Given the positive association between RAD21 alterations and telomeric content, we hypothesized that RAD21 alterations would negatively impact the median overall survival (mOS) of patients with cancer." (PMID 35227290, 2022). "Among the cohesin genes, it is RAD21 that is most frequently amplified in cancers." (PMID 34202641, 2021). "Increased levels of MYC and RAD21 can serve as indicators of dysregulated RS in cancer." (PMID 32859084, 2020). "Deregulation of RAD21 has been observed in a number of cancers." (PMID 32603365, 2020). "While Rad21 mutation is not common in advanced cancers, its depletion results in CIN in vertebrates." (PMID 26462024, 2015). "Aberrant RAD21 expression has been reported in multiple cancers and cancer cell lines." (PMID 21255398, 2011). "Across all cancer-related genes that were assessed, only RAD21 mutations (currently not considered actionable/targetable with approved drugs) had significantly higher prevalence in stage IV HR+/HER2− tumors compared to stage I-III disease (18.4% vs 9.7%; FDR = 0.04; OR 2.1, 95% CI: 1.4-3.2)." (PMID 40421962, 2025). "However, the precise mechanism by which RAD21 regulates the occurrence and development of cancers remains unclear." (PMID 38378967, 2024). "Unlike other subunits that are prone to mutation, RAD21 is most frequently amplified in cancers." (PMID 35860572, 2022). "While it can be difficult to identify the causative gene in a copy number amplification in cancer, we show that high telomeric content is associated with RAD21 and HGF but not nearby oncogenes, and furthermore, we identify a minimal amplified interval around RAD21 consisting of 8q23.1–q24.12." (PMID 35227290, 2022). "However, there is evidence that overexpressed RAD21 itself contributes to the pathology of cancer." (PMID 34202641, 2021). "This may help explain why MYC and RAD21 are frequently co-amplified in many cancers." (PMID 32859084, 2020). "Interestingly, recent studies have reported that Rad21 plays a role in several cancers." (PMID 28831167, 2017). "Failure to cleave RAD21 due to BRCA1-dependent caspase 3 inhibition may explain loss of HR repair in BRCA1 but not in BRCA2 cancers." (PMID 22537934, 2012). "Concurrently, the down-regulation of RAD21 expression, which inhibits the EMT process by modulating the 3D structure of chromatin, promotes the acquisition of cancer stem cell properties, which then enhances tumor aggressiveness." (PMID 40642059, 2025). "In support of this model, elevated expression of almost every cohesin subunit (RAD21, SMC1A, SMC3, STAG1, PDS5, WAPL) and cohesin regulator (NIPBL, MAU2) appears to be oncogenic and present in a wide range of cancer cells." (PMID 41370327, 2025). "Consistent with the findings in human cancer cell lines, the canonical IFN signaling genes such as Isg15, Ifi44, Ifit3, and Ddx58 were induced at a significantly higher magnitude in Rad21-knockdown cells upon IFN-β stimulation." (PMID 36201246, 2022). "The pan-cancer PCAWG dataset had a similar pattern as the FMI dataset, where both the ATRX/DAXX and RAD21 altered groups had higher telomeric content compared to WT samples." (PMID 35227290, 2022).
cancer (continued). "Interestingly, in two patients carrying RAD21 p.P298S/A we identified a known pathogenic KRAS hot-spot mutation as a common somatic denominator in the respective tumors, which is in line with a recently published association between cohesin complex mutations and RAS signaling in cancer progression." (PMID 35563565, 2022). "Investigating the proteins driving cluster 1, we found lower levels of circulating proteins regulating DNA repair/integrity (RBBP8, RAD21) and cell fate/replication (NOTCH3, TJP3, HNRNPA2), which play a role in cancer development." (PMID 35033985, 2022). "There are several other cancer-related genes on 8q, including HEY1 and RAD21, which are all candidates that we are currently evaluating." (PMID 33591953, 2021). "Of these, 22 genes were classified as transcription factors in MSigDB and 15 genes were found in the COSMIC Cancer Gene Census, including ERBB2 (Colo678), MYC (SW480), PPFIBP1 (IS1), and RAD21 (HT29)." (PMID 28683746, 2017). "Thus, under the cooperation of TGFβR2, CDKN1A and RAD21, the inhibition of DNA synthesis and the repair of DNA damage result in allowing cells to survival with the burden of potentially lethal cisplatin-induced cytotoxicity, and then cancer cells become resistant to cisplatin." (PMID 26482648, 2015). "Twenty of these genes are located in 8q22–q24 and 17q21, including PAPBC1, RAD21, ATAD2, MTSS1, SQLE, ST3GAL1, C17orf37, ABCC3 and PTPN2, previously reported as cancer-related genes." (PMID 21339811, 2011). "Tumor RAD21 overexpression strongly correlated with amplification of the RAD21 gene locus in a significant subset of high grade luminal, basal and HER2 cancers." (PMID 21255398, 2011). "Positive RAD21 expression was seen in 37% (75/201) luminal, 24% (10/42) basal, 22% (9/49) HER2 and 18% (5/28) null, cancers." (PMID 21255398, 2011). "In summary, our current study suggests that cohesin function is strongly regulated through Mcd1/RAD21 stability, and that manipulating its levels may have significant implications in cohesinopatheis and cancer research." (PMID 41370327, 2025). "As the PI3K-AKT pathway is known to regulate cell proliferation, cell death and motility to facilitate cancer development in various cancers, our results indicate that PI3K might be a potential downstream target of RAD21 in NSCLC." (PMID 38378967, 2024). "As expected, the network demonstrated that STAG2 and RAD21 could cross-talk with other modules, such as TGF-β signaling, pathway in cancer, the pluripotency of stem cells, and adenocarcinoma, in addition to the cell cycle." (PMID 35371307, 2022). "Targeting of GMPS, CKS1B, and RAD21 by 2 individual siRNAs attenuated colony-formation potential of cancer cells, while depletion of RAD54L failed to exhibit any effect on colony formation." (PMID 36201246, 2022). "Our previous work established that regions bound by BORIS alone in cancer cell lines were not occupied by cohesin subunits RAD21 and SMC3, indirectly suggesting that BORIS is not able to retain cohesin." (PMID 31937660, 2020). "In contrast, inactivation of the cohesin ring subunits SMC1A, SMC3, and RAD21 is not compatible with viability in both primary non-transformed human cells and human cancer cell lines." (PMID 30975996, 2019). "The discovery of fusion transcripts containing partners that regulate repair of DNA double-strand breaks and homologous recombination, such as RAD21, RDM1, BRCA2 and SHFM1, is consistent with abundant evidence for aberrant regulation of DNA replication in cancer." (PMID 24727804, 2014).
cancer (continued). "Because increased RAD21 expression may confer resistance to DNA-damaging agents, alternative treatment strategies may be useful in RAD21-positive BRCA2 and BRCAX cancers." (PMID 22537934, 2012). "In summary, our findings show that RAD21 expression is associated with a poorer prognosis in BRCA2 and BRCAX, but not in BRCA1 cancers." (PMID 22537934, 2012). "Aberrant regulation of RAD21 by mir-299-5p is also supported by a comparison of 11 BRCA1 basal and 13 normal breast samples, in which a sevenfold reduction in mir-299-5p was observed between BRCA1 cancers and normal breast tissue (P = 0.0002)." (PMID 22537934, 2012). "This is despite our finding that RAD21 does not correlate with survival in BRCA1 cancers and the higher use of chemotherapy in BRCA1 cancers." (PMID 22537934, 2012). "RAD21 mRNA expression correlated with DNA copy number, with amplification present in 32% (7/22) of luminal, 31% (4/13) of basal and 22% (2/9) of HER2 grade 3 cancers." (PMID 21255398, 2011). "However, the mechanistic effect of RAD21 or NIPBL in cancers, including NSCLC, is largely unclear, and further studies are needed to determine whether RAD21 or NIPBL could be an indicator for the use of PI3K inhibitors in NSCLC." (PMID 38378967, 2024). "An insufficiency of RAD21 that is not lethal can contribute to cohesinopathy or cancer." (PMID 35906355, 2022). "In addition, RAD21 expression was correlated with shorter survival in Grade 3 (p = 0.009) and but not in Grade 1 (p = 0.065) or 2 cancers (p = 0.090)." (PMID 35740618, 2022). "In addition, RAD21 expression level was negatively correlated with the majority of ISGs that were identified as direct targets of RAD21 and TEAD4, a relationship that was also observed in an analysis of RNA-Seq data from 1,377 human cancer cell lines (Cancer Cell Line Encyclopedia)." (PMID 36201246, 2022). "This suggests that CTCF, and most likely RAD21 and other factors such as REST, are driving the arrangement of nucleosomes and perhaps dictating DNA methylation patterns, offering a potential explanation for the substantial reorganization of NDRs to primarily overlap CTCF in the cancer cells." (PMID 24916973, 2014). "Similarly, RAD21 expression conferred a poor prognosis in grade 3, but not in grade 1 or 2 cancers." (PMID 22537934, 2012). "Similar to germ cells, depletion of CTCF and cohesin result in telomere damage in cancer cells, but unlike Smc1β−/− spermatocytes, TERRA levels are downregulated upon depletion of the cohesin component Rad21." (PMID 37636218, 2023). "RAD21 expression correlated with shorter survival in BRCA2 (P = 0.006) and BRCAX (P = 0.008), but not BRCA1 cancers (P = 0.713)." (PMID 22537934, 2012). "When compared to luminal cancers, null type cancers, but not basal and HER2 cancers, were significantly more likely to be RAD21 negative (P = 0.043)." (PMID 21255398, 2011). "Interestingly, RAD21 expression correlated with shorter survival in BRCA2 (p = 0.006) and BRCAX (p = 0.008), but not BRCA1 cancers (p = 0.713)." (PMID 35740618, 2022). "Interestingly, high RAD21 expression correlated with poorer survival in BRCA2 (P = 0.006) and BRCAX cancers (P = 0.008), but not in BRCA1 cancers (P = 0.71)." (PMID 22537934, 2012). "Further analysis of grade 3 tumors according to subtype showed a significant correlation between RAD21 expression and shorter RFS in the grade 3 luminal (P = 0.040), grade 3 basal (P = 0.018) and grade 3 HER2 cancers (P = 0.039), but not null type cancers (P = 0.247)." (PMID 21255398, 2011).